NCSTN (nicastrin)
Diseases named in the same sentence as NCSTN in open-access papers (continued):
Sharing a sentence is not in itself a finding about the gene and the disease.
PASH syndrome (1 paper, 2024). "Additionally, it is essential to explore why mutations in γ‐secretase complex genes such as NCSTN and PSENEN, known for causing HS, can also lead to PASH syndrome, which encompasses PG and acne." (PMID 38031879, 2024).
Stroke (1 paper, 2022). Sudden impairment of blood flow to a part of the brain due to occlusion or rupture of an artery to the brain. "Here, we also showed that photothrombotic stroke causes an increase in the level of γ-secretase proteins PS1 and nicastrin mainly in astrocytes and the administration of the inhibitor reduces the level of GFAP." (PMID 36289917, 2022). "In this work, we showed that photothrombotic stroke caused an increase in the level of γ-secretase protein subunits of presenilin-1 and nicastrin in astrocytes, but not in penumbra neurons." (PMID 36289917, 2022). "Little is known about the function of nicastrin in neuronal injury after stroke." (PMID 36289917, 2022).
viral infection (1 paper, 2025). "Severe viral infection predisposition was seen in 3 patients (POLR3A, IFIH1, TLR7XL) and bacterial susceptibility in 3 others (IRF4, IFNGR1, NCSTN)." (PMID 41209815, 2025).
tumor (15 papers, 2014 to 2025). "A higher NCSTN expression level was significantly associated with higher serum AFP level, tumor size as well as poorer tumor differentiation, indicating that the NCSTN was possibly correlated to HCC growth and progression." (PMID 32631394, 2020). "Compared with that in the shNC group treated with vector-NC plasmid, tumour growth in the group treated with vector-NCSTN plasmid was significantly inhibited." (PMID 32226312, 2020). "A meta-analysis of 9 HCC datasets vividly showed that only NCSTN expression was higher in tumour specimens than in normal liver tissues over 9 datasets." (PMID 32226312, 2020). "In univariate analysis, serum AFP level, status of ascites, tumor size, tumor number, macrovascular invasion, microvascular invasion and NCSTN expression were identified as potential variables correlated to OS or RFS of HCC patients." (PMID 32631394, 2020). "Consistently, NCSTN expression was much higher in tumor than in adjacent liver tissues at the mRNA level." (PMID 32631394, 2020). "On the other hand, the IHC results of 60 HCC patients further confirmed that NCSTN expression was higher in tumour specimens than in matched normal tissues." (PMID 32226312, 2020). "Nicastrin (NCSTN), a core subunit of γ-Secretase, has been reported to play a vital role in tumor progression." (PMID 32631394, 2020). "Our recent works showed that using monoclonal antibodies to target the extra-cellular domain of Nicastrin, the catalytic subunit of the GS complex, greatly reduced the tumor bulk in vivo and limits invasion and migration in vitro." (PMID 26093085, 2015). "However, on the whole, the study of NCSTN in tumor is still insufficient, and a lot of research is needed to reveal the more specific roles of NCSTN in tumor." (PMID 37928268, 2023). "In addition, incomplete expression of NCSTN is known to reduce the expression of miR-100-5p, which acts as a tumor suppressor involved in cell self-renewal and wound healing." (PMID 37760246, 2023). "NCSTN downregulation in HepG2 cells inhibited tumour growth ability in vivo." (PMID 32226312, 2020). "Indeed, 53 out of 60 HCC patients in our centre had higher NCSTN expression in tumour specimens than in paired normal tissues." (PMID 32226312, 2020). "The in vivo functions of NCSTN were illustrated by xenograft tumor models." (PMID 32631394, 2020). "Nicastrin expression correlates with age and tumor grade–and predicts worse tumor survival." (PMID 30515368, 2018). "To analyse the mRNA expression levels of NCSTN in 60 HCC patients, we analysed matched tumour and normal tissues by using qRT-PCR." (PMID 32226312, 2020). "The tumor volume and weight were dramatically higher in HCCLM3-shNC and Hep3B-NCSTN compared to those of corresponding HCCLM3-shNCSTN-2 and Hep3B-Vector, indicating that NCSTN promoted tumor growth in vivo." (PMID 32631394, 2020). "Cluster 1 was characterized by upregulation of tumor-suppressing genes: HNF1B, CCNDBP1, PATJ, EPB41L3, MARVELD2, PTEN in conjunction with cell-cycle genes – GSPT1, GPR19, EAPP, KIT, CDKL1, and stem cell markers – RBBP5, NANOG, NCSTN, ERG, including quiescent stem cell markers—FOXP1, SMARCA2." (PMID 36348001, 2022). "However, no study till now has examined the expression of NCSTN and its biological relevance in tumor progression in HCC." (PMID 32631394, 2020).
cancer (10 papers, 2014 to 2025). A tumor composed of atypical neoplastic, often pleomorphic cells that invade other tissues. "To test this hypothesis, we used bioinformatics analyses to analyse the underlying function of NCSTN in malignant tumours." (PMID 32226312, 2020). "We profiled the expression of Presenilin 1 and Nicastrin in 19 cancers within the Cancer Genome Atlas (TCGA) database using TIMER2.0 online web server, demonstrating that both genes had significantly higher expression in the several cancer types examined." (PMID 34059639, 2021). "Based on the GSEA results for TCGA data, we found that 54 signalling pathways, including cancer-related pathways and apoptosis pathways, were enriched in the high NCSTN expression group." (PMID 32226312, 2020). "To date, several monoclonal antibodies against NCSTN have been developed and have shown great efficacy in inhibiting cancer cell proliferation in vitro and in vivo." (PMID 32226312, 2020). "We also identified six predicted SQLE, CCT3, IDI1, GBA, MTR, and NCSTN cancer drug target genes." (PMID 31216110, 2019). "Our most important finding is a possible involvement of Notch-2 and its signalling pathway (dynamin-2, nicastrin, SPARC and PROS1) in dormancy of cancer spheroids in a HMW-HA concentration (5 wt%) representative of normal brain ECM." (PMID 40881990, 2025). "In addition, this correlation analysis revealed cancer-specific addiction associated with coordinated upregulation of another subset of genes that reside in the same region of chromosome 1 and are involved in vesicle and protein trafficking (GBA, GPR89A, NCSTN, PSMD4, VPS45)." (PMID 29535384, 2018).
infection (7 papers, 2010 to 2025). The state of being infected such as from the introduction of a foreign agent such as serum, vaccine, antigenic substance or organism. "The mRNA expression levels of NCSTN at different life stages of mixed-sex infection of S. mansoni were analyzed in reference to the RNA seq database." (PMID 39861031, 2025). "The transcripts of APP, ADAM10, BACE1, and subunits of the γ-secretase complex (PSEN1, PSEN2 APH1A and NCSTN) were significantly upregulated (p < 0.05) in at least one of the 4 investigated timepoints post-infection." (PMID 30786875, 2019). "In this protocol, when HaCaT GFP-BAP cells were infected with L2-BirA virus at 24 hours post-transfection, nicastrin siRNAs potently blocked infection with the L2-BirA virus." (PMID 28463988, 2017). "Similar results were seen in samples where expression of the γ-secretase component nicastrin was knocked down for 40 hours prior to infection with L2-BirA." (PMID 28463988, 2017). "Additionally, we established stable overexpression cell lines via a lentiviral infection in Hep3B and Huh7 cells, which exhibited relatively low endogenous NCSTN levels." (PMID 32631394, 2020). "These loci exhibited negative (ELN, SASH1, and SMAD7) and positive (CDSN, NCSTN, and PEX7) relationships between minor allele frequency and infection severity, with no overarching pattern evident in control loci lacking association with mange severity." (PMID 33664786, 2021). "In addition, the infection may also indirectly downregulate neutrophil function by downregulating functional related-genes of neutrophils, such as PYCARD and NCSTN." (PMID 35111158, 2021).
neurodegenerative disease (1 paper, 2023). A disorder of the central nervous system characterized by gradual and progressive loss of neural tissue and neurologic function. "We found that DCA, through its interaction with the Nicastrin subunit of γ-secretase, significantly contributed to the formation of amyloid beta, a key hallmark in the pathology of neurodegenerative diseases." (PMID 39883374, 2023).
NCSTN also shares sentences with these, for which no sentence is quoted: bacterial infection (2 papers); breast tumors (2); alopecia (1); aortic stenosis (1); basal cell carcinoma (1); cervical cancer (1); colorectal adenocarcinoma (1); cutis laxa (1); epidermal cyst (1); Glucose intolerance (1); hidradenitis (1); Hyperkeratosis (1); hyperplasia (1); ichthyosis (1); inflammatory skin disease (1); lentivirus infection (1); lobular carcinomas (1); melanoma (1); neuroblastoma (1); ovarian carcinoma (1); Palmoplantar keratoderma (1); psoriasis (1); schistosomiasis (1).